KIR3DL1 (killer cell immunoglobulin like receptor, three Ig domains and long cytoplasmic tail 1)
Description:
Receptor on natural killer (NK) cells for HLA Bw4 allele. Inhibits the activity of NK cells thus preventing cell lysis.
Synonyms: NKAT-3; NKAT3; NKB1; cl-2; cl-11; NKB1B; AMB11; CD158e1/2; CD158E1; CD158e2; KIR; KIR3DL1/S1
Tractability: Antibody: its Gene Ontology location is reachable by antibodies, with high confidence; UniProt places it where antibodies can reach, with medium confidence; UniProt predicts a signal peptide or a membrane-spanning region.
Gene: Protein-coding gene on chromosome 19 (54,816,468 to 54,830,778, forward strand). Ensembl gene ENSG00000167633.
Subcellular location: Cell membrane
Pathways (Reactome):
Immune System: Immunoregulatory interactions between a Lymphoid and a non-Lymphoid cell
Gene Ontology:
Molecular function: amyloid-beta binding; molecular adaptor activity; protein binding; HLA-B specific inhibitory MHC class I receptor activity; immune receptor activity; transmembrane signaling receptor activity
Biological process: natural killer cell mediated cytotoxicity; immune response; immune response-inhibiting cell surface receptor signaling pathway
Cellular component: plasma membrane
Genetic constraint (gnomAD): Loss-of-function variants: 48 observed, 33.28 expected, observed/expected ratio (o/e) 1.44, 90% interval 1.14 to 1.81. The synonymous counts are far from expectation, so gnomAD's model fits this gene poorly and the ratio says little. Missense variants: 649 observed, 498.63 expected, observed/expected ratio (o/e) 1.3, 90% interval 1.22 to 1.39. Synonymous variants: 251 observed, 187.4 expected, observed/expected ratio (o/e) 1.34, 90% interval 1.21 to 1.49.
Homologues: Orthologues: chimpanzee KIR3DL1 (75% identical), mouse Kir3dl1 (35% identical), mouse Kir3dl2 (34% identical), rat Kir3dl1 (33% identical), tropical clawed frog xilr1 (17% identical). Paralogues in human: KIR3DL2 (86% identical), KIR3DL3 (70% identical), KIR2DL1 (66% identical), KIR2DL3 (65% identical), KIR2DL4 (51% identical), LILRB1 (36% identical), LILRB3 (36% identical), LILRB2 (36% identical), LILRB5 (33% identical), KIR2DS4 (32% identical), LILRA6 (31% identical), LILRA1 (29% identical), and 13 more.
Diseases named in the same sentence as KIR3DL1 in open-access papers:
KIR3DL1 is named in the same sentence as 93 diseases in open-access papers, as found by Europe PMC text mining. Sharing a sentence is not in itself a finding about the gene and the disease. The quoted sentences say what the papers report.
AIDS (27 papers, 2008 to 2024). A syndrome resulting from the acquired deficiency of cellular immunity caused by the human immunodeficiency virus (HIV). "NK cells generated from KIR3DL1-Bw4 carriers were shown to strongly influence progression of acquired immune deficiency syndrome (AIDS) and plasma HIV RNA levels." (PMID 27490240, 2016). "The clinical relevance of KIR allelic variation is demonstrated by disease associations such as the association between possession of the KIR3DL1*004 allele and slower progression to AIDS or KIR3DL2*107 and early onset of allergic pathologies." (PMID 36719466, 2023). "Other KIR/HLA combinations associated with slower time to AIDS and lower viral load than seen in Bw6 homozygotes include KIR3DL1*004 + Bw4, KIR3DL1*h/*y + Bw4*80I, KIR3DL1*h/*y + B*27, KIR3DL1*l/*x + B*57 and KIR3DS1 + Bw4*80I." (PMID 35720328, 2022). "This evidence suggests that the expression of HLA-Bw4 alleles, in combination with KIR3DL1/S1, can be associated with resistance to both progression to AIDS and HIV infection in different HESN cohorts." (PMID 33042136, 2020). "The inhibition of KIR3DL1*h in the presence of Bw4 in association with slow progression to AIDS and lower VL via augmentation of NK functions seems contradictory." (PMID 30534128, 2018). "Examples of inhibitory receptors implicated in disease resistance are the association of KIR3DL1 and Bw4+ allotypes with slow AIDS progression and lower viral load in a cohort of over 1500 HIV+ individuals." (PMID 28695287, 2017). "Differences in expression levels of KIR3DL1 allotypes correlate with different functional capacities of NK cells, and KIR3DL1 allotypes expressed at high levels are associated with delayed progression to AIDS." (PMID 25506344, 2014). "KIR3DL1/3DS1 in combination with HLA-Bw4-80I allotypes (in particular HLA-B*57) are associated with slow progression to AIDS in human HIV infection." (PMID 25506344, 2014). "In patients expressing 80I isoforms of HLA-Bw4, KIR3DL1-high is associated with delayed AIDS onset compared with other isoforms of HLA-B." (PMID 24919192, 2014). "Epidemiological studies of human immunodeficiency virus 1 (HIV-1) infection indicate that a combination of HLA-Bw4-80I with either KIR3DL1 or KIR3DS1 is associated with delayed progression to AIDS." (PMID 25506344, 2014). "KIR3DL1 allotypes that are expressed at a high level on the NK cell surface associate with delayed progression to AIDS in HIV-infected individuals." (PMID 19008943, 2008). "Furthermore, the combined genotype of KIR3DL1+ and HLA-Bw4+ was strongly associated with slower progression to acquired immunodeficiency syndrome (AIDS) in human immunodeficiency virus (HIV) infection." (PMID 35273641, 2022). "Combinations of alleles at the polymorphic HLA-B locus and the NK cell surface killer immunoglobulin-like receptor locus KIR3DL1/S1 have been shown to influence time to AIDS in HIV-infected individuals and risk of seroconversion in HIV exposed seronegative (HESN) subjects." (PMID 25330014, 2014). "Patients with HIV have provided the first evidence that KIR3DL1 and HLA-B compound allotypes can variably influence disease outcomes, whereby highly-inhibitory combinations of Bw4-80I and KIR3DL1-high alleles best protect against progression to AIDS." (PMID 24919192, 2014). "Furthermore, in HIV-1 infection, high expression alleles of an inhibitory KIR, KIR3DL1, in the context of HLA-Bw4I have been associated with slow progression to AIDS." (PMID 22022261, 2011). "Moreover, high-expressing KIR3DL1 alleles have been associated with lower human immunodeficiency virus (HIV) viral load and slower progression to acquired immunodeficiency syndrome (AIDS)." (PMID 31156615, 2019). "The higher functionality, in terms of CCL4 secretion, of educated KIR3DL1+ NK cells may be a mechanism underlying the superior viral control and slower time to AIDS observed in epidemiological studies for some carriers of KIR3DL1hmz/Bw4 compared to carriers of other KIR/HLA genotypes." (PMID 28893287, 2017).
AIDS (continued). "In the context of other infectious diseases, the role of KIR3DL1 and their HLA ligands is controversial, with some studies associating them with protection from HIV and AIDs and others with disease severity in COVID-2019." (PMID 37647275, 2023). "Carriage of the KIR3DL1-high+HLA-B*57 genotype combination, which had the most potent effect on viral load control and slow time to AIDS in PLWH was significantly more frequent among IDU HESNs than in recently infected PLWH." (PMID 35746615, 2022). "The interactions between NK cell receptors (KIR3DL1 and KIR3DS1) and the protective HLA-B Bw4-80Ile on target cells are associated with delayed progression to AIDS has been documented." (PMID 35911681, 2022). "In contrast, patients with combinations of genes that predict for poorly-educated or uneducated KIR3DL1+ NK cells (i.e., HLA-Bw4-negative), progress rapidly to AIDS." (PMID 31627371, 2019). "In this sense, a protective effect of KIR3DL1*004 against the progression of the VIH infection to AIDS has been described." (PMID 31849952, 2019). "Variation in expression and density of KIR3DL1 has been shown to impact on AIDS progression in HIV-positive patients and on antibody-dependent cellular cytotoxicity against neuroblastoma cells." (PMID 30564239, 2018). "Additional partnerships of KIR3DL1 and HLA-Bw4 provide intermediate protection, and patients lacking HLA-Bw4 epitopes demonstrated the most rapid progression to AIDS." (PMID 24919192, 2014). "KIR3DL1/S1 subtypes have distinct biological activity and coding region variants of the KIR3DL1/S1 gene strongly influence pathogenesis of HIV/AIDS and other human diseases." (PMID 19008943, 2008). "For instance, expression of KIR3DL1*004 (in the context of self-HLA-Bw4) or that of KIR3DL1 allotypes expressed at high-density (in the context of self-HLA-Bw4*80I) have been described to delay AIDS progression." (PMID 36742337, 2023). "The aKIR allele at the KIR3DL1/S1 locus, KIR3DS1, in the presence of its Bw4-80I ligand, is associated with low setpoint HIV-1 viral load, slower progression to AIDS and low CD4+ T cell count and reduced occurrence of opportunistic infections in different HIV-1 infected cohorts." (PMID 36719466, 2023). "Not all the KIR3DL1/S1/HLA combined genotypes associated with a slower time to AIDS were also associated with protection from infection." (PMID 35746615, 2022). "Indeed, HLA-Bw4*80I downregulation could increase KIR3DL1 educated NK cell sensitivity and restrict AIDS progression." (PMID 36742337, 2023). "High KIR3DL1 cell surface expression in combination with HLA-B*57 bearing a Bw4 motif with Ile at position 80 (Bw4-80I) corresponds to delayed progression to acquired immune deficiency syndrome (AIDS) in comparison to patients lacking HLA-B*57." (PMID 34358058, 2021). "KIR3DL1*h has a higher affinity for Bw4-80I than Bw4-80T, resulting in greater inhibition of HIV and thereby slowing the progression to AIDS via elevated NK-cell polyfunction." (PMID 30534128, 2018). "The first descriptions implicating KIR3DS1/KIR3DL1 and HLA-Bw4 compound genotypes on HIV-1 disease outcomes emanated from epidemiological analyses of people living with HIV (PLWH) enrolled in the Multicenter AIDS Cohort Study." (PMID 39459918, 2024). "In line with this reasoning, studies of HIV infection show that NK cells from individuals with strong educating KIR3DL1–Bw4 interactions mount more efficient cytotoxic responses to HIV-infected cells and that such individuals are less likely to progress to AIDS." (PMID 37597015, 2023). "Because allele *004 is not expressed on the cell surface, slower progression to AIDS among individuals carrying KIR3DL1*004 + Bw4 implies a novel intracellular function for KIR3DL1* 004 or linkage disequilibrium with a neighboring locus that confers protection." (PMID 30534128, 2018).
AIDS (continued). "Progression to AIDS is significantly delayed in HIV-1 infected individuals carrying the HLA-Bw4 serological epitope, in particular those having isoleucine at amino acid position 80 (Bw4-80I), and certain allotypes of the inhibitory KIR3DL1 or the activating KIR3DS1 receptors." (PMID 26557119, 2015).
HIV-1 infection (15 papers, 2011 to 2025). The type species of lentivirus and the etiologic agent of acquired immunodeficiency syndrome (AIDS). "A study conducted in Burkina Faso reported that the KIR2DL2, KIR2DS2, KIR2DS3, KIR2DS4, and KIR3DS1 genes were associated with HIV-1 infection, while the KIR3DL1 gene was associated with protection against HIV-1 infection." (PMID 40244151, 2025). "In particular, the role of KIR3DL1/S1 in viral infections has been well-accepted since the first descriptions of significant associations between the KIR3DL1/S1 gene locus and the outcome of HIV-1 infection." (PMID 23125843, 2012). "Interestingly, both KIR3DS1(+) and KIR3DL1(+) NK cells are preferentially expanded in acute and chronic HIV-1 infection, respectively, but only in individuals also encoding for the HLA-Bw4 ligand family." (PMID 22807681, 2012). "We investigated the early effects of KIR3DL1 expression on CD8 T cells in individuals homozygous for the Bw4 or Bw6 genotype included during the acute/early phase of HIV-1 infection." (PMID 30147699, 2018). "Accordingly, KIR3DS1+ and KIR3DL1+ NK cells preferentially expand in response to HIV-1 infection in HLA-Bw4-80I+ individuals." (PMID 28708886, 2017). "In accordance with these genetic associations, NK cells expressing KIR3DS1 can suppress the in vitro replication of HIV-1 in HLA-Bw4-80I+ lymphocytes, and KIR3DS1+ and KIR3DL1+ NK cells preferentially expand during HIV-1 infection in HLA-Bw4-80I+ individuals." (PMID 26333068, 2015). "Furthermore, NK cells expressing KIR3DS1 and, to a lesser extent, KIR3DL1 specifically expand during acute HIV-1 infection in the presence of HLA-B Bw480I, the putative class I HLA ligand for these receptors." (PMID 40244151, 2025). "Additionally, co-carriage of the KIR3DL1 homozygous genotype (KIR3DL1*h/*y) together with HLA-B*57 was more frequent in HESN individuals compared to persons with acute HIV-1 infection (AHI)." (PMID 39459918, 2024). "In addition, both KIR3DS1- and KIR3DL1-positive NK cell proportions are elevated during acute HIV-1 infection in the presence of HLA-Bw4-80I molecules." (PMID 25506344, 2014). "Higher responsiveness of licensed NK cells might therefore serve as one potential underlying mechanism for the protective effect of the combined presence of KIR3DL1 and its cognate HLA ligands in chronic HIV-1 infection." (PMID 23125843, 2012). "The expansion of KIR3DL1+ and KIR3DS1+ NK cells that were dependent on the presence of the cognate Bw4 epitope were also monitored in patients during acute HIV-1 infection." (PMID 26557119, 2015). "KIR3DL1-positive CD8 T cells did not increase in acute/early HIV-1 infection, whereas the KIRs-positive CD8 T cells, including KIR3DL1, has been shown to increase in untreated individuals with chronic HIV-1 infection." (PMID 30147699, 2018). "Together, these results suggest that the KIR3DL1+CD8+ T cells do not play a crucial role in controlling HIV-1 infection and these CD8 T cells are not responsible for the beneficial effects observed in Bw4 homozygotes." (PMID 30147699, 2018). "This would indicate a KIR3DS1: HLA-Bw4I80:HLA-F protective axis in HIV-1 infection that is independent of KIR3DL1." (PMID 29184550, 2017). "Assessment of KIR2DL3 and KIR3DL1/DS1 did not reveal any significant differences between subsets of NK cells or the HIV-1 infection status of the subject." (PMID 24351015, 2013). "In addition, the higher frequency of early activated and proliferated CD8 T cells, and particularly of KIR3DL1-negative CD8 T cells in Bw4-homozygous individuals, would have greater antiviral potential during acute/early HIV-1 infection." (PMID 30147699, 2018).
COVID-19 (14 papers, 2021 to 2025). A disease caused by infection with severe acute respiratory syndrome coronavirus 2. "The KIR2DL1/HLA-C2 complex has been linked to increased disease severity, and the frequency of KIR2DS4 and KIR3DL1 genes has been associated with a risk of severe COVID-19, suggesting a significant role of these genetic markers in antiviral immunity." (PMID 40244151, 2025). "The presence of a combination of HLA-Bw4 and KIR3DL1 lowered the risk of developing severe COVID-19 by 58.8% (OR = 0.412, 95% CI = 0.165–0.904, p = 0.02)." (PMID 38202265, 2024). "The presence of the HLA-Bw4 and KIR3DL1 combination had a 58.8% lower risk of developing severe COVID-19 (OR = 0.412, 95% CI = 0.187-0.904, p = 0.02)." (PMID 36849422, 2023). "The study illustrated that KIR2DS4 is uniquely linked to severe cases of COVID-19, whereas both KIR2DS4 and KIR3DL1 are associated with mild, moderate, and severe manifestations of the disease." (PMID 40391199, 2025). "Therefore, the KIR3DL1 and HLA-Bw4 interaction may play a vital role in NK cell licensing, and loss of this strong interaction may underlie the increased risk of developing severe COVID-19." (PMID 36849422, 2023). "In conclusion, this study provides genetic evidence that inhibitory KIRs with HLA class I ligands, especially HLA-Bw4/KIR3DL1 interactions, exert protective effects against severe COVID-19 in a Chinese population." (PMID 36849422, 2023). "A significantly lower incidence of the low-affinity KIR3DL1+HLA-Bw4 T80+ combination (18.5 vs. 27.7%, p = 0.03, OR = 0.6, CI = 0.37–1.0) was observed in COVID-19 patients than the general population." (PMID 35273641, 2022). "Despite the small sample size, the inhibitory KIR3DL1 gene was more prevalent in individual CHB (100%) than in COVID-19 (96%) and HIV-positive (92%) individuals and significantly higher than in healthy controls (p = 0.021, OR = ∞)." (PMID 36555106, 2022). "The association of HLA-Bw4/KIR3DL1 in severe but not mild COVID-19 cases may be explained by the differential MHC-Ι expression in the infected individuals with high or low viral loads." (PMID 36849422, 2023). "Nonetheless, the reduced KIR3DL1/Bw4 pairs in severe patients and increased KIR2DL1/C2 pairs in mild patients indicate that the potency of NK cell education influences COVID-19 vulnerability." (PMID 36849422, 2023). "Future mechanistic studies are warranted to confirm the molecular basis of the decreased KIR3DL1+HLA-Bw4+ and KIR3DL2+HLA-A3/11+ gene combinations in dampening the effector functions of NK cells in COVID-19 patients." (PMID 35273641, 2022). "We observed that the KIR3DL1+HLA-Bw4+ and KIR3DL2+HLA-A3/11+ gene combinations were encountered at significantly lower frequency in COVID-19 patients than in the general population." (PMID 35273641, 2022). "The most striking feature of liver failure was the elevation of CCL23, FGF2, and KRLD1 and depression of KIR3DL1 at admission, while Gal-1 and DCN were decreased later during the history of COVID-19." (PMID 34177897, 2021). "Indeed, a lower frequency of KIR3DS1 was found in the mild COVID-19 group but not in the severe group, and a reduction in KIR3DL1 incidence was observed only in severe COVID-19." (PMID 36849422, 2023). "Finally, the inhibitory KIR3DL1 protein was found at higher expression levels in the COVID-19 negative controls as compared to the disease cohort." (PMID 37483595, 2023). "In a recent study of 424 COVID-19 positive patients (392 Saudi, 32 non-Saudi), the KIR2DS4 gene was associated with the highest risk of severe COVID-19 infection (OR 8.48, p= 0.0084) followed by KIR3DL1 (OR 7.61, p=0.0192)." (PMID 35874712, 2022). "KIR2DL1, KIR2DL3, KIR3DL1 and KIR3DL2 are inhibitory NK cell receptors and enhanced interactions via these receptors on CD8+ T cells could indicate a more balanced functional regulation of CD8+ T cells in mild COVID-19." (PMID 36591270, 2022).
COVID-19 (continued). "Notably, 40% of the COVID-19 patients were negative for both KIR3DL1+HLA-Bw4+ and KIR3DL2+HLA-A3/11+ combinations compared to 24.6% of the general population (OR = 2.04, p = 0.001, CI = 1.33–3.14)." (PMID 35273641, 2022). "Additionally, decreased expression of the inhibitory receptor KIR3DL1/DS1 was observed between the COVID-19 negative and COVID-19 positive groups." (PMID 37483595, 2023). "To better characterize these cells, we performed an extensive analysis of their cell-surface receptors early after inclusion (Pt1=Day 1 to 3); NK cells from COVID-19 patients were indistinguishable from those of the healthy donors concerning the following NK receptors: NKG2A, ILT-2 and KIR3DL1." (PMID 37342247, 2023). "Presumably, the reduced antiviral defense due to the absence of KIR3DL1+HLA-Bw4+ and KIR3DL2+HLA-A3/11+ interactions coupled with exuberant hyperinflammatory response mediated by activating KIR2DS1 and 2DS5 arbitrate the development of severe COVID-19." (PMID 35273641, 2022).